DIAPH2-AS1 (DIAPH2 antisense RNA 1)
Description:
May function as an early signal that helps mediate the activation of T-cells.
Synonyms: EPAG
Gene: Long non-coding RNA gene on chromosome X (97,431,286 to 97,642,589, reverse strand). Ensembl gene ENSG00000236256.